EGFR (epidermal growth factor receptor)
Diseases named in the same sentence as EGFR in open-access papers (continued):
Sharing a sentence is not in itself a finding about the gene and the disease.
colorectal cancer (continued). "Currently, inhibitors targeting the epidermal growth factor receptor (EGFR) are being used for colorectal cancer treatment; however, the available drugs are still limited." (PMID 39766211, 2024). "The epidermal growth factor receptor (EGFR) plays an important role in colorectal cancer by activating key signaling pathways, such as Ras-MAPK and PI3K-Akt, which drive tumor growth, angiogenesis, and survival." (PMID 39684219, 2024). "Essential genes for tumor evaluation include EGFR, KRAS, BRAF, and PIK3CA, which play critical roles in the progression of colorectal cancer and in the selection of targeted therapies as anti-EGFR monoclonal antibodies (MoAbs)." (PMID 39338229, 2024). "Downstream of EGFR and KRAS, the protein kinase encoded by the V-Raf murine sarcoma viral oncogene homolog B1 (BRAF) gene is affected by mutations detected in 5–15% of colorectal cancer patients." (PMID 39722096, 2024). "Src is similarly important for colorectal cancer pathogenesis, as Src activity is required both for epidermal growth factor receptor (EGFR) and vascular endothelial growth factor (VEGFR) signaling, and zelenirstat has potent antiangiogenic effects." (PMID 38837078, 2024). "The overall association scores of CHI3L1, EGFR and VEGF with colorectal cancer were 0.079, 0.555, and 0.596, respectively." (PMID 38177294, 2024). "Recently, EGFR inhibitors, such as cetuximab, leucovorin, and oxaliplatin, have been used to treat colorectal cancer." (PMID 38193944, 2024). "Since EGFR is overexpressed in a variety of malignancies, including colorectal cancer (CRC), it is a great candidate for targeted cancer treatment." (PMID 39590368, 2024). "HER2 can dimerize with EGFR in colorectal cancer, influencing responsiveness to EGFR-targeted therapies such as cetuximab." (PMID 39062682, 2024). "Clinical trials using rechallenge strategies with anti-EGFR therapies in patients with colorectal cancer and ctDNA evaluation." (PMID 38711991, 2024). "Of note, the numerical difference in response rates for BRAFi/MEKi versus anti-EGFR/BRAFi combinations in colorectal cancer is moderate, being 12% for the former but only 26% for the latter." (PMID 38612902, 2024). "For example, in colorectal cancers overexpressing EGFR, the presence of a strongly activating KRAS mutation eliminates the effectiveness of EGFR-targeting antibodies, even in tumors with highly overexpressed EGFR." (PMID 38639476, 2024). "We analyzed 4122 colorectal cancer patients receiving anti-EGFR antibodies from the Center for Cancer Genomics and Advanced Therapeutics database, identifying 54 patients (1.3%) with rare RAS variants undetectable by standard testing." (PMID 39727997, 2024). "Mutations in RAS genes are common in patients with colorectal cancer (CRC), occurring in nearly 40% of all CRC cases, and result in resistance to treatment with epidermal growth factor receptor (EGFR) monoclonal antibodies." (PMID 39682112, 2024). "EGFR is overexpressed in 60–80% of colorectal cancers (CRCs), making anti-EGFR targeting a crucial strategy in CRC treatment." (PMID 39695128, 2024). "Other cancers, like colorectal cancer, can have EGFR amplification and can show an enhanced EGFR signal in plasma from these patients." (PMID 38830977, 2024). "They evaluated two targeting approaches to reach colorectal cancer cells: anti-EGFR antibodies (Ab) and anti-EGFR aptamers attached to the surface of PTX-QDM." (PMID 38675202, 2024). "The most notable interactions occur between CBD and EGFR, KRAS, BRAF, and MEK1, as reflected by docking scores and being the most critically mutated or dysregulated proteins in colorectal cancer." (PMID 39194723, 2024). "Cetuximab, an approved monoclonal antibody to target epidermal growth factor receptor (EGFR) in colorectal cancer, has been shown to upregulate phagocytosis of EGFR overexpressing cancer cells, leading to enhanced T-cell-mediated anti-tumor immune response." (PMID 38256021, 2024).
colorectal cancer (continued). "Patient‐derived colorectal cancer organoids function as practical and effective in vitro tools for investigating the tumour response to EGFR‐targeted therapy." (PMID 39245957, 2024). "For example, in the monitoring of advanced colorectal cancer, ctDNA enables the dynamic and repeated assessment of changes in multiple key molecules of the tumor, such as EGFR, ERBB2, PIK3CA, and MAP2K1, among others." (PMID 39184861, 2024). "A previous study suggested that targeting the extracellular domain of EGFR is promising in colorectal cancer treatment where there is resistance to EGFR inhibitors cetuximab and panitumumab." (PMID 38216592, 2024). "LR004 is a novel chimeric (human/mouse) monoclonal antibody developed for the treatment of advanced colorectal carcinoma with detectable epidermal growth factor receptor (EGFR) expression." (PMID 38276624, 2024). "This is most likely due to the heterogeneous molecular background of colorectal carcinomas, suggesting that EGFR expression status should be evaluated in resection specimens rather than in pre-op biopsy samples to obtain optimal results." (PMID 38650801, 2024). "Because of its overexpression in 25–82% of colorectal carcinomas, EGFR has been identified as an invaluable therapeutic target for colorectal carcinoma metastases." (PMID 38276624, 2024). "In fact, in recent studies, even the efficacy of anti-EGFR therapy has been demonstrated to differ depending on tumor location because of the molecular heterogeneity of colorectal carcinomas." (PMID 38650801, 2024). "While EGFR overexpression has previously been reported in 25-77% of colorectal carcinomas, we detected EGFR expression in 88.2% of biopsy specimens and in 91.2% of surgical specimens." (PMID 38650801, 2024). "Results of a phase II trial of cetuximab serving as a single agent in patients with chemotherapy–refractory EGFR-overexpressing colorectal cancer showed it is well tolerated but has modest activity." (PMID 38201251, 2023). "Only 18% of colorectal cancer patients in the last decade with Kirsten rat sarcoma viral oncogene homolog (KRAS) wild-type tumors received anti-epidermal growth factor receptor (EGFR) antibodies." (PMID 37308981, 2023). "Most of the time, the amount of EGFR protein is increased on the outer surface of colorectal cancer cells, which helps the cancer cells to grow." (PMID 37920521, 2023). "As a second-line treatment for RAS/BRAF wild-type colorectal cancer, treatment regimens using anti-EGFR antibodies are recommended by regional guidelines as one of the standard treatments." (PMID 37760533, 2023). "Examples of targets used in FME are epidermal growth factor receptor (EGFR, overexpressed in colorectal cancer) and vascular endothelial growth factor A (VEGFA, present in early stages of colorectal neoplasms and Barrett’s dysplasia)." (PMID 35764908, 2023). "Most patients with skin reactions after the pre-emptive strategy who received an anti-EGFR inhibitor had milder grades of colorectal cancer in this study." (PMID 36980549, 2023). "MET amplification has been detected after anti‐EGFR antibody treatment of KRAS‐wild‐type colorectal cancer." (PMID 36416133, 2023). "To date, liquid biopsy, using qPCR, has been approved by FDA and EMA for the detection of EGFR mutations in non-small cell lung cancer (NSCLC) and Kras mutations in colorectal cancer (CRC)." (PMID 37542343, 2023). "Anti-EGFR (epidermal growth factor receptor) therapies, such as Cetuximab, are chimeric monoclonal antibodies widely used to curb colorectal cancer metastasis by blocking the activation of EGFR tyrosine kinases, thereby preventing further cell proliferation." (PMID 37114077, 2023). "Human EGFR-targeting monoclonal antibody (mAb) therapy such as cetuximab has been approved for clinical use in patients with colorectal cancers and head and neck squamous cell carcinomas." (PMID 37489364, 2023).
colorectal cancer (continued). "Mutations in codon 61 in KRAS and NRAS were detected more frequently in colorectal cancer patients with anti-EGFR therapy resistance than before the initiation of anti-EGFR therapy." (PMID 36836537, 2023). "In their preclinical studies, vemurafenib was combined with EGFR inhibitors like cetuximab and gefitinib and tested in colorectal cancer cell lines." (PMID 36801912, 2023). "BRAF inhibition introduced by V600E mutation causes a rapid feedback activation of human epidermal growth factor receptor (HER)/epidermal growth factor receptor (EGFR) in colorectal cancer cell lines." (PMID 36624452, 2023). "Epidermal Growth Factor (EGF) and EGFR levels are significantly higher in malignant zones of colorectal cancer specimens than in other nearby regions." (PMID 37296986, 2023). "Conversely, inhibition of EGFR markedly enhanced sensitivity to AZ’1569 in all KRASG12CMT colorectal cancer cells, supporting the findings of a recent study." (PMID 36279564, 2023). "Surprisingly, RasGRP1 acts as a tumor suppressor in colonic epithelium; furthermore, RasGRP1 can be used as a biomarker for predicting the efficacy of anti-epidermal growth factor receptor (EGFR) therapy for CRC (colorectal cancer) patients." (PMID 36675167, 2023). "Emerging therapeutic regimens with encouraging results in the wild-type (WT) KRAS colorectal cancer (CRC) setting include inhibitors of epidermal growth factor receptor (EGFR) and glutaminolysis." (PMID 36961000, 2023). "Further investigations with respect to effect of monensin on EGFR in colorectal cancer cells are required." (PMID 36896461, 2023). "The same concept has been validated in colorectal cancer individuals treated with the anti-EGFR antibodies cetuximab or panitumumab." (PMID 38304035, 2023). "We found that our highest-ranked predicted targets were significantly enriched in targets with FDA-approved therapeutics for colorectal cancer (p-value < 0.025) that included EGFR, VEGFA, and PTGS2." (PMID 37790614, 2023). "Due to the significance of the EGFR axis in the development of cancer and advancement of tumors, the potential of EGFR expression as a prognostic biomarker in patients with colorectal cancer (CRC) has been examined." (PMID 37895912, 2023). "EGFR is overexpressed in 25–77% of colorectal cancer, which is related to the poor prognosis of cancer patients." (PMID 37799727, 2023). "Its potential role in other EGFR-expressing malignancies, such as head and neck cancer and colorectal cancer, will need further assessment in other clinical trials." (PMID 36879012, 2023). "The combined therapy with EGFR, BRAF, and MEK inhibition has shown efficacy in BRAF-mutated colorectal cancer, demonstrating the clinical value of using ERBB inhibition to enhance targeting of an MAPK oncogene." (PMID 36752207, 2023). "In KRAS mutant colorectal cancer lines with combined EGFR and MEK inhibitor resistance, compensatory PI3K/AKT signaling plays an important escape mechanism." (PMID 37154160, 2023). "As in colorectal cancer, therapy with epidermal growth factor receptor (EGFR)-inhibitors shows promising results." (PMID 37359934, 2023). "Given the critical role of these pathways in cancer cell growth, EGFR represents a significant therapeutic target for the treatment of colorectal cancer metastases." (PMID 37686423, 2023). "However, another study indicated that colorectal cancer patients with a 2.3~10% KRAS mutant allele burden in tumor tissue might be resistant to anti-EGFR therapy, and suggested that a >2.3% MAF detected in tumor tissue should be considered positive for KRAS mutation." (PMID 37511664, 2023). "Anti-KRAS antibodies can be used in combination with anti-EGFR antibody (Cetuximab) in KRAS wildtype advanced colorectal cancer (CRC) patients to concurrently kill tumor cells that has developed resistance to anti-EGFR therapy due to acquired KRAS mutation." (PMID 37051535, 2023).
colorectal cancer (continued). "Meanwhile, EGFR‐LFD was identified in colorectal cancer and cholangiocarcinoma which, to the best of our knowledge, has not been reported." (PMID 36622089, 2023). "Overall, this review provides historical context, current clinical usage, and future directions for anti-EGFR antibodies in advanced colorectal cancer." (PMID 37774394, 2023). "Cetuximab, an agent used to treat advanced colorectal cancer, was used to study the effect of inhibiting EGFR in bladder cancer." (PMID 36855119, 2023). "The study identified a significant increase in expression levels of epidermal growth factor receptor (EGFR) in CD24+ colorectal cancer (CRC) cells." (PMID 38137380, 2023). "In 2003, Buchanan and co-workers demonstrated that PGE2 induces the migration and invasion of colorectal cancer cells through rapid transactivation and phosphorylation of EGFR." (PMID 37190301, 2023). "EGFR overexpression is found in 25 to 82% of colorectal cancer cells and is a useful target in the treatment of colorectal cancer metastasis." (PMID 37762323, 2023). "Up to 60–80% of colorectal cancers overexpress EGFR (epidermal grow factor receptors), which are tyrosine-kinase receptors, and this is an important component in the initiation and progression of colorectal cancer." (PMID 37626641, 2023). "Higher ERK signaling rebound driven by strong reactivation of EGFR limits the efficacy of KRASG12C inhibitors in KRASG12C mutant colorectal cancer." (PMID 37221195, 2023). "In particular, the EGF/EGFR pathway caught our attention since EGFR has been shown to be overexpressed in colorectal cancer patient populations but its prognostic value in this tumor progression remains still unclear." (PMID 37853459, 2023). "BRAF and KRAS are two key oncogenes that determine response to anti-EGFR therapies in colorectal cancer patients." (PMID 37483495, 2023). "Anti-EGFR antibodies (cetuximab or panitumumab) have a therapeutic effect in patients with colorectal cancer." (PMID 37626641, 2023). "The next highly researched target antigen is the Epidermal Growth Factor Receptor (EGFR), which is primarily overexpressed in solid tumors such as lung, pancreatic, and colorectal cancers." (PMID 37987250, 2023). "In particular, due to Vemurafenib resistance in colorectal cancer an anti-EGFR antibody, Cetuximab, needed to be combined for this tumour specific cohort." (PMID 37217528, 2023). "EGFR expression has been used as a biomarker to treat colorectal cancer (CRC) patients with wild-type KRAS in the US (patients with metastatic CRC and HNSCC in the EU)." (PMID 37519889, 2023). "In agreement with our findings, it was shown that TRAP1 is a determinant of metabolic rewiring in colorectal cancer and favors resistance to the EGFR inhibitor, cetuximab." (PMID 37508418, 2023). "Because these inhibitor pairs did not suppress cancer cell stemness, we aimed to study the effectiveness of a triple drug combination against BRAF, MEK, and EGFR that was used in a clinical trial for patients with BRAFmut colorectal cancer." (PMID 37791907, 2023). "Because of these functions, the overexpression of EGFR confers great advantages on tumoral cells in epithelial cancers, such as in 15–30% of breast cancers, 60% of lung cancers, and 80% of colorectal cancers." (PMID 37509078, 2023). "For this reason, targeted monoclonal antibodies that bind to EGFR, such as cetuximab, inhibit the proliferation of colorectal cancer cells by blocking intracellular signal transmission." (PMID 37920521, 2023). "Mutual regulation has also been confirmed in other studies, indicating that increased expression of both ABCG2 and EGFR (metastatic marker) is positively correlated with resistance to anoikis and metastatic potential in the colorectal cancer cell population." (PMID 37445716, 2023).
colorectal cancer (continued). "Pelitinib as an EGFR-TK inhibitor has been evaluated in phase 2 clinical trials for colorectal cancer and NSCLC, but the molecular mechanisms of its anti-cancer effects from the perspective of EMT on HCC cell lines have not been studied to date." (PMID 37495969, 2023). "EGFR is commonly expressed in advanced colorectal cancers (CRCs), leading to one of the first molecular targeted therapies." (PMID 37712424, 2023). "This review provides historical context, current clinical usage, and future directions for anti-EGFR antibodies in advanced colorectal cancer." (PMID 37774394, 2023). "The co-administration significantly reduces the cetuximab dose required for the antiproliferative activity against colorectal cancer cell line E705, which is sensitive to EGFR-targeted therapy." (PMID 38003308, 2023). "In 2007, it has been reported that the use of NS-398, a selective COX-2 inhibitor, and AG1478, an EGFR inhibitor, reduced the migration of colorectal cancer cells." (PMID 37190301, 2023). "Increased gene amplification has been reported in several cases of colorectal cancer as an independent prognostic marker for anti-EGFR monoclonal antibodies." (PMID 37111291, 2023). "An Italian, multicenter, retrospective study analyzed 277 colorectal cancer cases treated with anti-EGFR antibodies in first-line treatment and angiogenesis inhibitors in second-line treatment." (PMID 37760533, 2023). "EGFR pathway is an adaptive mechanism of resistance in colorectal cancer and that concurrent EGFR pathway inhibition is needed in the treatment of BRAF V600-mutant colorectal cancer." (PMID 36801912, 2023). "Previous research found that Menin is closely associated with glycometabolism and Menin inhibitors induced increase in glycolysis occurs in an mTOR-independent manner, which enhances the sensitivity of colorectal cancer cells to EGFR inhibitors." (PMID 36928253, 2023). "Only a small fraction of EGFR positive advanced colorectal cancers expressing wild type KRAS respond to anti-EGFR mAbs, and acquired resistance also commonly occurs." (PMID 37170144, 2023). "CNVs were determined across a set of 10 lung, breast, and colorectal cancer samples harboring a total of 11 known CNVs in the EGFR, MET, and ERBB2 genes as determined by orthogonal methods, including the OPA, OFA, and INFORM HER2 FISH assays." (PMID 37762091, 2023). "For example, in skin carcinoma cells, pancreatic adenocarcinoma, or human colorectal carcinoma, TRPV1 suppresses posttranslational modification of the epidermal growth factor receptor (EGFR) associated with pro-proliferative pathways." (PMID 37507867, 2023). "A similar result for EGFR was found when human colorectal carcinoma cells (MIP-101) were studied under conditions of μg." (PMID 36674696, 2023). "Between 44 and 97% of patients with colorectal cancer overexpress EGFR on immunohistochemical analysis." (PMID 35453596, 2022). "The EGFR-targeted nanoparticles delivery effectively enhanced the inhibition of colorectal cancer growth in a mouse model, suggesting EGFR as a promising target for liposomal drug delivery systems." (PMID 35918704, 2022). "This study aimed to synthesize new thioderivative chalcones and analyze their impact on the NF-κB, STAT3, EGFR and Nrf2 signaling pathways in colorectal cancer cells." (PMID 36050500, 2022). "The EGFR monoclonal immunoglobulins cetuximab/panitumumab can thus be used to treat colorectal cancer." (PMID 35455247, 2022). "EphB3 induction was observed in EGFR-inhibitor-resistant colorectal cancer and FGFR-inhibitor-resistant gastric cancer." (PMID 36291790, 2022). "We then used PLA analysis to look for in vivo interactions between EGFR and EphA2 in both normal and cancerous cells using lung and colorectal cancer patient tissues." (PMID 35668076, 2022).